CD4 (CD4 molecule)
Diseases named in the same sentence as CD4 in open-access papers (continued):
Sharing a sentence is not in itself a finding about the gene and the disease.
tumor (continued). "MicroRNA miR-138 was suggested to function as a tumour suppressor and has been shown to target CTLA-4 and programmed cell death 1 (PD-1) in CD4+T cells." (PMID 32054041, 2020). "Tumors were harvested 20 days post tumor inoculation and analyzed by comparing the percentage of CD8+ and CD4+ cells in the CD45+ cell population, as well as the percentage of Treg+ cells in the CD45+/CD4+/foxP3+ cell population." (PMID 33218169, 2020). "It has been suggested that the inhibition of ZAP-70 tyrosine-phosphorylation is a mechanism of CTLA-4 mediated suppression of CD4+ T activation, indicating a central role of ZAP-70 kinase activity in T cell activation and anti-tumor immune responses." (PMID 33194762, 2020). "Further, in the resected tumor specimen at 6 weeks following RT/HTRT, significantly higher number of CD4+ cells were evident in the RT-treated part whereas significantly higher number of macrophages (CD68+) were observed in the part treated with HTRT." (PMID 32596144, 2020). "As shown with biaxial plots, we identified a population of CD4+ Foxp3+ tumor-infiltrating MAIT cells and validated them by flow cytometry on additional CRC tumor infiltrate samples." (PMID 33205061, 2020). "Administration of GDC-0919 alone limited the tumor proportions of CD3+ lymphocytes and CD4+ T cells, which were also shown to be less activated based on the IFNgamma staining." (PMID 32194552, 2020). "The results showed that numbers of the CD4+ T and CD8+ T cells in the spleen were increased in each of the tumor-bearing mice compared with the healthy mice." (PMID 32823603, 2020). "The primary objective is to determine DNA methylation and DNA repair levels before, and immediately after treatment; quantify immune-response markers (PDL-1, PD-1, CD4/CD8, and CD68) in blood, tumor and microenvironment before treatment and after 2 cycles." (PMID 32569203, 2020). "The tumors with NEAT1 knockdown M109 cell harvested from mice had intratumoral elevation in CD45+ CD3+ T cells and CD4– CD8+ T cells compared to tumor from control mice." (PMID 32296457, 2020). "When compared to other immune cells in tumor tissues, CD8 T cells, resting CD4 memory T cells, macrophages M0, and macrophages M2 are the four immune cells with the highest abundance (relative fraction >0.05 in both risk groups)." (PMID 33031392, 2020). "Through immunohistochemistry (IHC) using specific antibodies for CD4 and CD8, T cells were located throughout Aza-treated tumor tissue within 48 h after receiving initial treatment." (PMID 32296439, 2020). "PtenΔ/ΔBRF1Tg tumours contained significantly fewer stromal CD3 and CD4 T cells (p = 0.0438, 0.0394, respectively) but stromal CD8 or FOXP3 (a marker for regulatory T cells) T cells were not altered." (PMID 31740786, 2020). "Two indolent TLPD patients demonstrated CD4+ T-cells in the tumor, and one ALCL patient had CD30+, CD4+ and TIA1+ tumor cells." (PMID 33087157, 2020). "Microglia/macrophages (CD68+) and T cells (CD4+ and CD8+) were still detected in the microscopically visible residual core of the tumor (Hoechst)." (PMID 33266255, 2020). "Combination therapy can increase CD4+ and CD8+ T cell infiltration and prolong the survival of tumor-bearing mice." (PMID 32000802, 2020). "Compared to that in pPBMCs, the proportions of exhausted CD4+ and CD8+ T cells were distinctly higher at the tumor sites." (PMID 32457755, 2020). "The expression of the activation markers CD69 and CD44 was substantially upregulated on CD4+ and CD8+ tumor-infiltrating T cells in M1-treated mice, indicating the reinvigoration of T-cell populations." (PMID 33311488, 2020). "CD4+ T helper lymphocytes (Th), CD8+ CTLs, and B cells each play a role in coordinating an initial primary and a long-term memory anti-tumor response that destroy emerging lesions." (PMID 35310881, 2020).
tumor (continued). "Secondly, they promote the cross-presentation of antigens to CD4+ and CD8+ T cells, which result in the long-term antitumor memory of CD4+ and CD8+ T cells after tumor fragments are internalized by antigen-presenting cells (APCs)." (PMID 33015169, 2020). "FCM analysis showed that percentages of CD4 and CD8 positive T cells were increased in the splenic and tumor lymphocytes." (PMID 33643911, 2020). "Mouse studies show that blockade of the CTLA-4 and PD-1 receptors synergistically induce CD4 and CD8 T cell numbers in the tumor microenvironment (TME)." (PMID 32547707, 2020). "TCRβ+CD8+CD4+ cells, which only constituted between 0.22 and 3.4% of CD45+ lymphocytes in unaffected and 0.2–4% in tumor tissue, were also insufficient for functional experiments." (PMID 32185408, 2020). "CD4+ Th and CD8+ CTL populations increase with tumor malignancy, starting at 39% in WHO grade II tumors, rising to 73% in WHO grade III, and 98% in grade IV." (PMID 33329549, 2020). "As such, assessing lymphocyte densities as ratios such as CD8/FOXP3 or CD4/CD8 has been investigated and has shown to have prognostic potential in certain tumor types, but warrants further validation and systematic investigation." (PMID 33013886, 2020). "Of note, prior to tumor injection blood samples contained a comparable distribution of WT Thy1.1+ CD45.2+ and Siah2−/− Thy1.2+ CD45.2+ in the CD4+ and CD8+ pools." (PMID 31911617, 2020). "cDC1, marked by CD141+ in human and CD103+ in mouse, excels in cross-presentation and priming of tumor antigens to CD8+ T cells; cDC2, marked by CD1c+ in human and CD11b+ in mouse, mainly primes CD4+ T cells." (PMID 33329692, 2020). "Antibiotics diminish myeloid-derived suppressor cells and increase antitumor M1 macrophages to promote Th1 differentiation of CD4+ T cells and CD8+ T cell activation in the tumor." (PMID 32817793, 2020). "Similar results of the contrasting percentages of CD4+ and CD8+ T cells in tumor tissues were also detected and confirmed by flow cytometry." (PMID 32813937, 2020). "The immune-inflamed phenotype was characterized by the presence of both CD4 and CD8 expressing T cells in the tumor parenchyma, and these immune cells were positioned in proximity to the tumor cells." (PMID 32612211, 2020). "Macrophages, CD4+ T and FOXP3+ T cells are strong promoters of angiogenesis in tumours, explaining some of our findings." (PMID 32946040, 2020). "Similar to that observed in TC-1 tumor model, AnxA5-AH5 administration following cisplatin significantly increased the CD8+ T cell and CD4+ T cell populations and reduced the Tregs and MDSCs population in the TME." (PMID 32111835, 2020). "STAT3 is the main factor promoting tumor growth by activating CD4+ regulatory T cells, which ultimately suppress CD8+ cytotoxic T cells and enhance tumor growth." (PMID 33050544, 2020). "Evading immune-surveillance through macrophage/MDSC-mediated suppression of anti-tumor CD8+ and CD4+ T-cells is a common strategy used by tumors to promote metastasis." (PMID 33233625, 2020). "Conversely, the frequencies of TNF-α+ and/or IFN-γ+ cells in splenic CD4+ and CD8+ cells were significantly lower in Lsp1 Tg mice than in WT mice after tumor inoculation." (PMID 33020243, 2020). "IL‐17 exerted anti‐tumor functions by recruiting neutrophils, NK cells, and CD4+ and CD8+ T cells to tumor tissue and enhancing NK cell and cytotoxic T lymphocyte (CTL) activation." (PMID 31903715, 2020). "In in vivo studies we observe synergistic tumour growth delays and elevated levels of CD4+ and CD8+ cells in tumours receiving adjuvant drug combination." (PMID 32243973, 2020). "Except for malignant neoplastic cells, TIICs including CD4 T cells, CD8 T cells, Treg, macrophage, DC, and NK cells also play important roles in shaping the tumor microenvironment." (PMID 32923385, 2020).
tumor (continued). "The lower tumor development in mice harboring TGF-β-DNR CD4+ T cells correlated with a reduced frequency of IL-17A+IL-22+ CD4+ T cells, whereas IL-17A-IL-22+ CD4+ T cells were unaffected." (PMID 32451418, 2020). "Consistently, the HFD-stimulated infiltration of total, CD4+, and CD8+ T cells into tumor-seeded eFats was prevented in TLR4-cko mice." (PMID 33060562, 2020). "Recently, subpopulations of CD4 and CD8 T cells stratified by PD-1 expression in the tumour microenvironment were reported to be important prognostic factors in cancer immunotherapy." (PMID 32277125, 2020). "Increased CD8+ and reduced CD4+CD25+ regulatory T cells (Tregs) were consistently detected in blood and tumor tissues from mice treated with BMDCTEX-N1ND compared with other groups." (PMID 32286296, 2020). "For primary tumors, in particular, pro-cancerous regulatory T and Th2 helper T cells, and anti-cancerous CD4+ memory T, CD8+ T, Th1 helper T, and M1 macrophage cells were increased in the high-score tumor group of both TCGA and METABRIC cohorts." (PMID 32331421, 2020). "Despite difference across individuals, proportion of CD4+, CD8+, and PD-1+ T cells show significantly different distribution between tumor or non-tumor tissues." (PMID 33145436, 2020). "To assess the mechanism of NARA1leukin’s anti-tumor effects, we analyzed the composition of tumor-infiltrating lymphocytes (TILs) with a particular interest in the ratio of CD8+ T to CD4+ Foxp3+ Treg cells." (PMID 33353953, 2020). "The now activated APCs engulf any foreign particles including the tumour cells and presents the antigen at their major histocompatibility complex II (MHCII) for recognition and engagement with CD4 + T-helper cells." (PMID 32612457, 2020). "4T1 tumor-bearing BALB/c mice showed more intermediate- and high-frequency CD4+CD25+ T cells CDR3 repertoires; there were also some specific CD4+CD25+ T cells that showed high-frequency proliferation." (PMID 33029539, 2020). "Our results indicated that all components of TRIMELVax were required for an efficient activation of cellular and humoral responses and for controlling tumor growth in a CD8+ and CD4+ T-cell-dependent manner." (PMID 32690772, 2020). "They play a critical role in maintaining host-tolerance and thus preventing auto-immunity, by regulating other immune cells including DCs, NK cells, B-cells, CD4+ and CD8+ T cells, but in doing so also facilitate tumor immune escape and tumor progression." (PMID 32602047, 2020). "This antigen presentation of CD4 T cells when in an acute setting will further recruit and activate CD8+ T cells to kill the identified tumor cells." (PMID 32911646, 2020). "It has been demonstrated that anti-Clec9A nanoemulsion bearing OVA or its CD8 and CD4 epitopes can efficiently induce CTL and T helper responses, as well as inhibit tumor growth in mice bearing PyMT-ChOVA breast cancer cells." (PMID 32150821, 2020). "In mouse models, a combination of these AKT-inhibited CD4+ and CD8+ CAR T cells showed better anti-tumor effects compared to control CAR T cells." (PMID 32504246, 2020). "T-bet-deficient CD4+ T cells were able to control tumor growth even more effectively than WT CD4+ T cells in CD8 T-cell-depleted mice, supporting the relevance of CD4+GzmB+ T cells in tumor control induced by αCTLA-4." (PMID 31924474, 2020). "In this study, we performed RNA sequencing of both CD8 T cells and CD4 T cells based on the expression patterns of PD-1 and TIM-3 and aimed to clarify those characteristics and the differences stratified by tumour grade in RCC patients." (PMID 32277125, 2020). "While CD8+ T and CD4+ TH1 cells suppress angiogenesis and induce vascular maturation by secreting IFN-γ, they are unable to infiltrate the TME due to malformed tumor vessels." (PMID 32913278, 2020).
tumor (continued). "Contributing mechanisms included CD4+ T cell-mediated induction of CXCL9 and CXCL10 in the tumor microenvironment to attract CXCR3-expressing CD8+ T cells or to confer a specific cytotoxic CD8+ T cell effector program amongst others." (PMID 32610710, 2020). "Determination of immune-cold tumours by combined low-density cell counts of CD3, CD4 and CD8 immunohistochemistry constituted the best prognosticator across stage II–IV CRC, particularly in patients with stage IV disease (HR 1.98 [95% CI: 1.47–2.67])." (PMID 32684627, 2020). "The low levels of CCR7 on CD4+ and CD8+ T cells in the tumor tissue compared to the blood of tumor patients are shown in representative density plots." (PMID 32082401, 2020). "BH3 mimetics pre-sensitized tumor cells facilitated the CAR-T cell proliferation, with superior expansion of both CD4+ and CD8+ subsets." (PMID 33362794, 2020). "We further demonstrate that during the later stages of tumor development in Nod2−/− mice, STAT3 and ERK are activated, and there are increased numbers of neutrophils, inflammatory monocytes, and CD4+ T cells in the blood and liver." (PMID 33239685, 2020). "We show that a fraction of both CD4+ and CD8+ T cells, which have infiltrated the tumor stroma, also express PD‐1." (PMID 32615027, 2020). "The median nearest neighbor distance from tumor to immune cells are 2.9 um for CD16+ myeloid, 23.2 um for CD3 + CD4-CD8- T-cells, 44.5 um for CD4+ helper T-cells, 24.0 for CD8+ cytotoxic T-cells, and 56.9 μm for CD20+ B-cells, respectively." (PMID 32723384, 2020). "DCs need stimulation of CD40 by active CD4+ T cells, so human DCs expressing high CD40L lead to increased activation of reactive T cells with low immunogenic tumour antigens." (PMID 32610601, 2020). "Different proportions of Regulatory T cells (Tregs) including naive B cell, resting CD4+ T cells memory, resting dendritic cells, CD8+ T cells were identified between tumor tissues and normal tissue." (PMID 33173412, 2020). "HSD increased the frequencies of CD4+ T and CD8+ T cells within CD45+ cells by ~50% in these tissues of both 4T1 and B16F10 tumour models." (PMID 32265505, 2020). "The CXCR3 ligands CXCL9, CXCL10 and CXCL11 were all elevated in the tumour, suggesting that the CXCL9/CXCL10/CXCL11–CXCR3 axis is involved in both CD4+ and CD8+ T cell infiltration into the tumour." (PMID 32439888, 2020). "As the infiltration of TIL subsets was correlated with one another, we also analyzed the relationship between the ratios of TIL (FOXP3+/CD8+ TIL, FOXP3+/CD4+ TIL, and CD4+/CD8+ TIL) and tumor recurrence." (PMID 32216826, 2020). "To evaluate the association between peripheral NLR and intratumoral inflammatory markers, we analyzed neutrophils and CD8, CD4, and CD163+ cells from paired primary and recurrent tumor specimens." (PMID 33330078, 2020). "We further assessed the changes of several key immune cells in the tumor microenvironment, including MDSCs and T cells (CD4+ T and CD8+ T cells) in blood, spleen and tumor in the 4T1 tumor-bearing mice." (PMID 32290071, 2020). "To determine which type of CAR-T cells contribute more to antitumor effect in vivo, we isolated human CD4+ and CD8+ T cells, polarized them in vitro under Th9- or Th1-culture condition, and injected them into tumor-bearing mice." (PMID 33214555, 2020). "In our study, nsPEF increased the infiltration of T cells, particularly CD4+ T lymphocytes the CD4+/CD8+ ratio was significantly higher than in the anti-PD-1 group, in which tumor-infiltrating cells were predominantly CD8+ T cells." (PMID 32802733, 2020). "Therapeutic Aza treatment correlated with an overall increase in tumor immune infiltrate with specific increases in CD4 and CD8 T cells, indicating an important role for adaptive anti-tumor immunity in tumor control." (PMID 32296439, 2020).
tumor (continued). "Intriguingly, milk fermented by Lactobacillus casei CRL 431 also retarded tumour growth in the same model of breast cancer, and serum levels of IL-6 were reduced, whereas the ratio of CD8+/CD4+ T lymphocytes was increased." (PMID 32575876, 2020). "We found that the infiltrated cDC1, CD4+, and CD8+ T cells in the tumor-burdened lungs were significantly decreased by CCL7 deficiency." (PMID 33257678, 2020). "Another subset of auxiliary T cells, the T follicular helper (Tfh) CD4+ lymphocytes, defined by CXCR5 chemokine receptor expression and the Bcl6 transcription factor, are found within and around CRC tumor nests and tumor draining lymph nodes (tdLN)." (PMID 33381121, 2020). "Interestingly, the percentage of dHGP at the tumour–liver interface was negatively associated with the relative proportion of CD4+ T cells in tumour-free liver samples (β = −0.103, p = 0.021), and positively associated with the CD8+/CD4+ ratio (β = 0.022, p = 0.026)." (PMID 32418992, 2020). "CD4 and CD8 single-positive T cells showed more favorable characteristics for anti-tumor immunotherapy in B3/C than in non-B3/C according to the WHO classification." (PMID 32132638, 2020). "Consistently in vitro, T cells in the tumor microenvironment were higher in CG-745 (CD4 (8.62%) and CD8 (7.19%)) than in vehicle group (CD4 (1.73%) and CD8 (1.51%))." (PMID 32368288, 2020). "Memory T cells are involved in the downregulation of tumor proliferation rate, and DLBCL patients with less than 20% of infiltrating CD4+ cells have an inferior failure-free survival and overall survival." (PMID 32731512, 2020). "To address this, we isolated CD4+ cells, macrophages, and PMN-MDSCs from the spleen of PyMT tumor-bearing mice and analyzed the expression mRNA levels of IL-31Ra." (PMID 32843492, 2020). "To investigate whether dLNs derived Tfr cells were involved in tumor control, we set up BM chimera mice by mixing bone marrow cells derived from Foxp3DTR mice (50%) and Cxcr5–/– mice (50%) and injecting the mixtures into sub-lethally irradiated CD4–/– recipients." (PMID 32477338, 2020). "Finally, CIBERSORT, which also estimates the relative proportion of the different immune types within each sample, indicated that M2 macrophages and T cells (particularly CD8 and CD4 memory resting) were the most abundant immune populations, irrespective of tumor site or mutation status." (PMID 33048845, 2020). "Taken together, these experiments demonstrate that the in situ gel vaccine loaded with GM-CSF, Dox-iRGD, and CpG enhances tumor-specific CD8+ and CD4+ T-cell activity in tdLNs and the systemic circulation, and slows the growth of 4T1 tumors." (PMID 33173046, 2020). "After vaccination, brain biopsies revealed significant infiltration of focal CD4+, CD8+, CD56+ and IFN γ producing T cells against autologous tumor-derived peptides bound to HSP-96." (PMID 33228738, 2020). "The results showed that the frequencies of tumor-infiltrating CD3+ and CD4+ T cells were similar between WT and Lsp1 Tg mice." (PMID 33020243, 2020). "Early infiltration of tumors by immune cells such as pro-inflammatory macrophages, both CD4 and CD8 T lymphocytes, NK, and DCs is crucial for tumor control." (PMID 32714330, 2020). "We performed a preliminary investigation of immune cells, and the results showed a significant infiltration of DCs, CD4+ and CD8+ T cells in the tumor tissue from YYWY-treated Lewis-bearing mice." (PMID 32595493, 2020). "Increased lymphocytes at the tumor site were detected 24 h after ALA-PDT, and remained elevated for at least 72 h, being CD4+ more abundant than CD8+ lymphocytes." (PMID 31991650, 2020). "Immunohistochemistry confirmed that subcutaneous tumours and liver metastases in Fgf2LMW−/− mice had increased infiltration by T cells (CD3+ cells, both CD4 and CD8), which extended into the clusters of tumour cells." (PMID 32792542, 2020).